PKN3 (protein kinase N3)
Diseases named in the same sentence as PKN3 in open-access papers (continued):
Sharing a sentence is not in itself a finding about the gene and the disease.
tumor (continued). "Atu027 is the delivery vehicle used, containing siRNAs against PKN3, which is the downstream effector of the phosphoinositide-3-kinase signaling pathway PKN3, in order to decrease tumor development and lymph node metastases to solid tumors and is now being explored in a clinical trial." (PMID 35745769, 2022). "Furthermore, we have demonstrated the importance of the PKN3–p130Cas interaction for PKN3‐stimulated cell growth and invasiveness in vitro and tumor growth in vivo." (PMID 30422386, 2019). "Stromal PKN3 is enriched in primary endothelial cells as well as in osteoclasts, being apart from tumor cells among the few normal cell types with significant amount of PKN3; this is consistent with the usually invasive features of endothelial cells in particular." (PMID 30422386, 2019). "In summary, we suggest that aberrantly expressed PKN3 and p130Cas can cooperate in cancer progression and tumor growth and therefore may represent an attractive target for therapeutic intervention." (PMID 30422386, 2019). "Therefore, it is conceivable that PKN3 blocker would target both tumor cells and stromal cells when used as a potential cancer therapy." (PMID 26742562, 2016). "We have demonstrated, the critical role of PKN3 in stromal cells in regulation of tumor metastasis." (PMID 26742562, 2016). "If so, what is the potential mechanism of the block of tumor cell extravasation in PKN3 KO mice?" (PMID 26742562, 2016). "Our data provide the first in vivo genetic demonstration that PKN3 plays critical roles in angiogenesis and tumor metastasis, and that defective maturation of cell surface glycoproteins might underlie these phenotypes." (PMID 26742562, 2016). "What is the immediate upstream regulator of PKN3 in angiogenesis and tumor metastasis?" (PMID 26742562, 2016). "The difference in number and size of the metastatic tumors may arise from the substantial disturbance of tumor cell extravasation in PKN3 KO mice than in WT control." (PMID 26742562, 2016). "Therefore, the glycosylation defect of ICAM-1 might be involved in the inhibition of tumor cell extravasation in PKN3 KO mice." (PMID 26742562, 2016). "Protein kinase N3 (PKN3) is a downstream effector of the phosphoinositide-3-kinase (PI3K) pathway and its inhibition in vascular and lymphatic endothelial cells suppresses tumor progression and lymph node metastasis." (PMID 34631795, 2021). "Inhibition of tumour PKN activity has been explored as an oncology therapeutic approach, with a PKN3-targeted RNAi (RNA interference)-derived therapeutic agent in Phase I clinical trials." (PMID 27919031, 2014). "PKN3 was found to be upregulated in various tumour cell lines, and PKN1 overexpression has been correlated with tumour grade in prostate cancer." (PMID 21754995, 2011). "Although PKN3 KO mice appeared indistinguishable from their WT counterparts, this model also indicated the role of host stromal PKN3 in tumor progression." (PMID 30422386, 2019). "The relationship between the suppression of growth factor-induced angiogenesis and tumor metastasis has not been clarified, but the PKN3 KO mouse experiment clearly revealed that the host PKN3 is crucial for tumor metastasis." (PMID 26742562, 2016). "Additional feature observed in HUVECs knocked down of PKN3 was defective glycosylation of ICAM-1, a central adhesion molecule important for binding and signaling between vascular endothelial cells and tumor cells during the tumor metastasis." (PMID 26742562, 2016). "PKN3 has been considered the primary player in PKN-dependent tumour cell invasion with no role for PKN1 or PKN2." (PMID 21754995, 2011). "Accordingly, systemic administration of siRNA‐lipoplex (Atu027) directed against PKN3 and targeting mainly the stromal compartment rather than the pathologically defined tumor entity, prevented lung metastasis in lung experimental and spontaneous breast metastasis models in a dose‐dependent manner." (PMID 30422386, 2019).
tumor (continued). "So, why does PKN3 appear not necessary during tumor angiogenesis?" (PMID 26742562, 2016). "However, our data showed that PKN3 ablation had no impact on tumor angiogenesis, consistent with the previous report describing the orthotopic cancer model treated with Atu027 evaluated by CD31 or CD34 immunoreactivity." (PMID 26742562, 2016). "However, it is not clear whether PKN3 in the host stromal cells has a role in tumor metastasis." (PMID 26742562, 2016). "In the tumour cell line 5637 with relatively enriched expression of PKN2 compared to other cells tested, we were able to detect a strong phenotype just by depleting PKN2, with PKN1 depletion having a weaker effect and PKN3 none at all." (PMID 21754995, 2011).
cancer (10 papers, 2013 to 2025). A tumor composed of atypical neoplastic, often pleomorphic cells that invade other tissues. "While the expression of PKN1 and PKN2 is ubiquitous in most of the adult tissues, the expression of PKN3 is restricted mainly to endothelial cells, osteoclasts and several cancer cell types." (PMID 33092266, 2020). "The role of PKN3 in tumorigenesis was identified in early reports, which showed that PKN3 mRNA is scarce in normal human adult tissues but abundantly expressed in numerous cancer cell lines." (PMID 30422386, 2019). "Atu027, a siRNA-lipoplex targeted against protein kinase N3 (PKN3), prevented lung metastasis in a phase I trial of various cancer models." (PMID 24275949, 2013). "Recently, we have identified interaction between PKN3 and adaptor protein p130Cas (Crk-associated substrate; BCAR1 in human) which promotes the pro-malignant growth of cancer cells and could partly explain PKN3-mediated phenotype." (PMID 33092266, 2020). "Furthermore, the enrichment of PKN3 mRNA in some cancer cell lines as well as its requirement in malignant prostate cell growth suggested its involvement in oncogenesis." (PMID 26742562, 2016). "Therefore, targeting PKN3 in host stromal cells has a therapeutic potential for the prevention of cancer metastasis." (PMID 26742562, 2016). "Thus it is still promising that in some conditions PKN3 blocker suppresses the primary cancer growth in a cell autonomous-fashion." (PMID 26742562, 2016). "Although PKN3 is an important effector kinase of small Rho GTPases and a key player in regulation of processes such as cytoskeleton organization, proliferation and promotion of malignant growth of various cancer types, its downstream signaling remains largely understudied." (PMID 33092266, 2020). "The expression profile of stromal PKN3 might act as a prognostic marker of cancer." (PMID 26742562, 2016). "PKN3 expression is regulated by the PI3K signaling pathway, specifically through the catalytic subunit p110β, contributing to angiogenesis and invasive cancer cell behavior." (PMID 40717965, 2025). "Another siRNA drug, Atu027, is encapsulated inside a lipid nanoparticle (LNP) to target the protein kinase N3 (PKN3), an essential gene for cancer growth and metastasis." (PMID 36918935, 2023). "We showed that phosphorylation of ARHGAP18 by PKN3 leads to activation of its GAP domain and contributes to regulation of active RhoA levels, implying the possible crosstalk of PKN3 and ARHGAP18 signaling in cancer and other diseases." (PMID 33092266, 2020). "Although none of these 20 ncRNAs are targeting FAK or PYK2, most are used to treat cancers, and two are specifically silencing kinases (SYK and PKN3)." (PMID 29891810, 2018). "Target gene candidates in cancer therapy are mainly involved in oncogenes, angiogenesis and proliferation, like PLK1, EphA2, RRM2, KRAS, PKN3 and VEGF, which have been tested as target genes in early-phase clinical trials for RNAi-based cancer therapies." (PMID 30065155, 2018).
PKN3 also shares sentences with these, for which no sentence is quoted: prostate tumor (2 papers); bladder cancer (1); cognitive decline (1); colorectal cancer (1); dementia (1); metastatic tumors (1); osteoporosis (1); pachyonychia congenita 1 (1); periodontal disease (1); prostate adenocarcinoma (1); rheumatoid arthritis (1); sarcopenia (1).